DLST (dihydrolipoamide S-succinyltransferase)
Description:
Dihydrolipoamide succinyltransferase (E2) component of the 2-oxoglutarate dehydrogenase complex. The 2-oxoglutarate dehydrogenase complex catalyzes the overall conversion of 2-oxoglutarate to succinyl-CoA and CO(2). The 2-oxoglutarate dehydrogenase complex is mainly active in the mitochondrion. A fraction of the 2-oxoglutarate dehydrogenase complex also localizes in the nucleus and is required for lysine succinylation of histones: associates with KAT2A on chromatin and provides succinyl-CoA to histone succinyltransferase KAT2A.
Synonyms: OGDC-E2; DLTS; KGD2; PGL7; PPGL7
Tractability: PROTAC: ubiquitination databases record sites on it; its protein half-life has been measured.
Target class: Enzyme; Transferase
Gene: Protein-coding gene on chromosome 14 (74,881,891 to 74,903,966, forward strand). Ensembl gene ENSG00000119689.
Subcellular location: Mitochondrion matrix; Nucleus
Subcellular location (Human Protein Atlas): Nucleoplasm; Cytosol; Mitochondria
Pathways (Reactome):
Metabolism: Glycine degradation; OADH complex synthesizes glutaryl-CoA from 2-OA; OGDH complex synthesizes succinyl-CoA from 2-OG
Metabolism of proteins: Protein lipoylation
Gene Ontology:
Molecular function: acyltransferase activity; dihydrolipoyllysine-residue succinyltransferase activity; protein binding
Biological process: tricarboxylic acid cycle; 2-oxoglutarate metabolic process; generation of precursor metabolites and energy; succinyl-CoA metabolic process; 2-oxoglutarate decarboxylation to succinyl-CoA
Cellular component: membrane; mitochondrion; nucleoplasm; nucleus; oxoadipate dehydrogenase complex; oxoglutarate dehydrogenase complex; mitochondrial matrix
Genetic constraint (gnomAD): Loss-of-function variants: 17 observed, 52.2 expected, observed/expected ratio (o/e) 0.33, 90% interval 0.22 to 0.49. The upper end of that interval is the gene's LOEUF score, 0.49, which puts it in group 2 of 6, group 1 being the genes least tolerant of losing a copy. Missense variants: 512 observed, 595.87 expected, observed/expected ratio (o/e) 0.86, 90% interval 0.8 to 0.92. Synonymous variants: 206 observed, 206.13 expected, observed/expected ratio (o/e) 1, 90% interval 0.89 to 1.12.
Homologues: Orthologues: chimpanzee DLST (100% identical), macaque DLST (98% identical), dog DLST (95% identical), mouse Dlst (92% identical), pig DLST (90% identical), rat Dlst (87% identical), rabbit DLST (86% identical), tropical clawed frog dlst (75% identical), zebrafish dlst (74% identical), Caenorhabditis elegans dlst-1 (58% identical), Drosophila melanogaster CG5214 (57% identical). Paralogues in human: DLAT (31% identical), PDHX (26% identical), DBT (25% identical).
Diseases named in the same sentence as DLST in open-access papers:
DLST is named in the same sentence as 37 diseases in open-access papers, as found by Europe PMC text mining. Sharing a sentence is not in itself a finding about the gene and the disease. The quoted sentences say what the papers report.
breast carcinoma (6 papers, 2016 to 2024). "The TCA cycle: High expression of dihydrolipoamide S-succinyltransferase (DLST/2-oxoglutarate dehydrogenase complex [OGDC]) and malic enzyme (ME2) is associated with poor prognosis in breast cancers." (PMID 37046596, 2023). "In the GSE145548 cohort, knockdown of ATF2 in breast cancer cells MCF7 resulted in the dramatic change of cuproptosis regulators (DLST, GCSH, PDHA1, LIPT1 and DLD)." (PMID 36733399, 2022). "The data suggested that the four genes, AP2B1, APP, GPNMB and DLST, were highly expressed in breast cancer and that AP2B1 was a suitable prognostic marker for breast cancer." (PMID 35678671, 2022). "The human protein atlas database also found that AP2B1, APP, GPNMB and DLST were highly expressed in breast cancer and that AP2B1 (cut-off value, 75%) was significantly associated with survival rate (p = 0.044)." (PMID 35678671, 2022). "The present study identified four genes (AP2B1, APP, GPNMB and DLST) that were significantly downregulated by luteolin in breast cancer cell lines." (PMID 35678671, 2022). "Intriguingly, dihydrolipoamide S-succinyl-transferase (E2 component of 2-oxo-glutarate complex) (DLST), a metabolic enzyme of Krebs cycle, was upregulated in MCF-7 breast cancer cells, but downregulated in PC3 prostate cancer cells." (PMID 38249992, 2024). "In addition, the HPA database demonstrated that AP2B1, APP, GPNMB and DLST were highly expressed in breast cancer; the increased expression of AP2B1 (cut-off value, 75%) was significantly associated with the survival rate (p = 0.044) of 1075 patients with breast cancer." (PMID 35678671, 2022).
neuroblastoma (6 papers, 2023 to 2024). Neuroblastoma (NB) is the most common solid, extracranial childhood tumor. "Overexpression of the dihydrolipoamide S-succinyltransferase (DLST) is associated with poor outcome in neuroblastoma patients and triple-negative breast cancer (TNBC) and specifically with the oxidative phosphorylation (OXPHOS) pathway." (PMID 36634214, 2023). "Recently, an increased expression of the dihydrolipoamide S-succinyltransferase (DLST) gene has been shown to predict poor outcome of neuroblastoma and triple-negative breast cancer (TNBC)." (PMID 36634214, 2023). "Moreover, loss of dihydrolipoamide S-succinyltransferase (DLST) that modulates entry of glutamine into the TCA cycle, impeded progression of MYCN-amplified neuroblastoma by impairing NADH production and OXPHOS activity." (PMID 37414143, 2023). "Dihydrolipoamide S-succinyltransferase (DLST) is an oncoprotein highly expressed in BC, including MCF7, MDA-MB-231 BC cell lines, and TNBC as well as in neuroblastoma." (PMID 37834160, 2023). "DLST (dihydrolipoamide S-succinyltransferase), a tricarboxylic acid (TCA) cycle enzyme, is an important mediator of MYC-driven leukemogenesis, and promotes tumor aggression in neuroblastoma." (PMID 38439957, 2024). "DLST is an E2 component of the α-ketoglutarate (αKG) dehydrogenase complex, which governs the entry of glutamine into the TCA for oxidative decarboxylation, thus promotes neuroblastoma aggression." (PMID 36891150, 2023). "Our in-depth investigation of DDX1 coamplification revealed a previously unanticipated and fundamentally new role of DDX1 in cellular metabolism by uncovering its interaction with the α-KGDH complex as a noncanonical interaction partner of the DLST subunit in neuroblastoma cells." (PMID 38197697, 2024).
gastric cancer (3 papers, 2022 to 2025). A primary or metastatic malignant neoplasm involving the stomach. "We conducted molecular experiments to validate our findings, and the results of Western blot analysis revealed notable disparities in the expression levels of FDX1, LIAS, DLAT, DLST, GCSH, PDHB and PDHA1 in gastric cancer cells between the CSRS‐Low (AGS) and CSRS‐High (HGC‐27) subtypes." (PMID 38898987, 2024). "DLST SLC31A1, LIPT1, and UBE2D1 are reported to regulate cuproptosis in sepsis, hepatocellular carcinoma, multiple myeloma, thyroid carcinoma, oral squamous cell carcinoma, rheumatoid arthritis, periodontitis, gastric cancer, colorectal cancer, and myocardial infarction." (PMID 40980812, 2025).
periodontitis (3 papers, 2023 to 2025). An acute or chronic inflammatory process that affects the tissues that surround and support the teeth. "Among these, four CRGs were found to be down-regulated in chronic apical periodontitis (CAP), namely Nuclear Factor Erythroid 2-Related Factor 2 (NFE2L2), Dihydrolipoamide S-Succinyltransferase (DLST), Solute Carrier Family 25 Member (SLC25A3), and Glycine Cleavage H Protein (GCSH)." (PMID 40909264, 2025).
triple-negative breast carcinoma (3 papers, 2021 to 2025). An invasive breast carcinoma which is negative for expression of estrogen receptor (ER), progesterone receptor (PR), and human epidermal growth factor receptor 2 (HER2). "DLST, the E2 component of the 2-oxoglutarate dehydrogenase complex, was identified as a dependency in subsets of triple-negative breast cancer, where its high expression was associated with poor prognosis." (PMID 41157129, 2025).
colorectal cancer (2 papers, 2025). A primary or metastatic malignant neoplasm that affects the colon or rectum. "The study revealed that, compared to normal tissues, genes FDX1, DLD, DBT, DLST, and DLAT were significantly downregulated in colorectal cancer tissues, while LIPT1, GCSH, and ATP7B genes were upregulated." (PMID 40276654, 2025).
glioma (2 papers, 2023). A benign or malignant brain and spinal cord tumor that arises from glial cells (astrocytes, oligodendrocytes, ependymal cells). "Furthermore, Cox regression analysis in the TCGA database showed that FDX1, LIPT1, DLD, DLAT, SLC31A1, ATP7A, and DLST might be risk factors; however, LIAS, ATP7B, and GCSH were significant preventive factors for gliomas." (PMID 37515314, 2023). "The expression of GLS (p < 0.001), LIPT1, FDX1, SLC31A1 (p < 0.01), DLST, CDKN2A, PDHA1, ATP7A, ATP7B, and NFE2L2 (p < 0.05) was different between glioma and adjacent tissues." (PMID 36936439, 2023).
melanoma (2 papers, 2022 to 2023). A malignant, usually aggressive tumor composed of atypical, neoplastic melanocytes. "Moreover, we detected that PD-L1 expression was positively correlated with some cuproptosis-related genes (CDKN2A, FDX1, LIPT1, and MTF1), but negatively correlated with other cuproptosis-related genes (ATP7B, DLST, and PDHA1) in an analysis of 470 melanoma patients." (PMID 35837286, 2022).
Sepsis (2 papers, 2025). Sepsis is defined as life-threatening organ dysfunction caused by a dysregulated host response to infection. "The expression of SLC31A1, CD274, ATOX1, MTF1, UBE2D1, DLD, and VEGFA was found to be upregulated, while that of DLST, UBE2D2, COX11, DLAT, GLS, FDX1, and ULK2 were significantly downregulated in patients with sepsis-associated ALI." (PMID 38779731, 2025).
Alzheimer disease (1 paper, 2025). A progressive, neurodegenerative disease characterized by loss of function and death of nerve cells in several areas of the brain leading to loss of cognitive function such as memory and language. "Moreover, mutations in the DLST gene have been associated with neurodegenerative diseases, including Alzheimer's disease (AD) and Parkinson's disease (PD) in different populations around the world." (PMID 40609475, 2025).
atherosclerosis (1 paper, 2019). A disease characterized by the build-up of fatty material and calcium deposition in the arterial wall resulting in partial or complete occlusion of the arterial lumen. "It has recently been reported that the levels of miR-146-5p and its targets NUMB and DLST are strongly linked to TMAO levels and may be involved in the progression of atherosclerosis." (PMID 31741723, 2019).
Dilater cardiomyopathy (1 paper, 2024). "The remaining pathways were all detected with a predominance of control proteins, such as the Citrate cycle (TCA cycle) (P-value < 0.0001; ACLY, DLST, PDHA1, PDHB), except Dilater cardiomyopathy (DCM) (P-value = 0.0006; ACTB, ADCY8, LOC396781, TPM1)." (PMID 38409238, 2024).
non-small cell lung carcinoma (1 paper, 2024). A group of at least three distinct histological types of lung cancer, including non-small cell squamous cell carcinoma, adenocarcinoma, and large cell carcinoma. "Dihydrolipoamide S-acetyltransferase and dihydrolipoamide S-succinyltransferase, key genes in cuproptosis, were proven to be associated with non-small cell lung cancer prognosis and metastasis." (PMID 39654205, 2024). "Dihydrolipoamide S-acetyltransferase and dihydrolipoamide S-succinyltransferase may serve as predictive markers for metastasis in non-small cell lung cancer." (PMID 39654205, 2024).
osteoporosis (1 paper, 2025). A condition of reduced bone mass, with decreased cortical thickness and a decrease in the number and size of the trabeculae of cancellous bone (but normal chemical composition), resulting in increased fracture incidence. "It showed that in osteoporosis patients, CP (P < 0.01), LIPT1 (P < 0.05), SLC25A3 (P < 0.001), and UBE2D3 (P < 0.01) were upregulated, while the expression levels of CDKN2A (P < 0.05), DBH (P < 0.01), DLST (P < 0.05), LOXL2 (P < 0.05), SLC31A1 (P < 0.05), and UBE2D1 (P < 0.01) were downregulated." (PMID 40980812, 2025).
sick sinus syndrome (1 paper, 2015). A constellation of signs and symptoms which may include syncope, fatigue, dizziness, and alternating periods of bradycardia and atrial tachycardia, which is caused by sinoatrial node dysfunction. "Hence, thorough genetic analysis might reveal a modifying or even causal role of DLST gene variants in the pathogenesis of cardiac pacemaker diseases, such as the sick sinus syndrome." (PMID 25697682, 2015).
tumor (23 papers, 2012 to 2026). "In addition, circRNA dihydrolipoamide S-succinyltransferase (circDLST) stimulated tumor growth in GC." (PMID 35435117, 2022). "OGDH subunit E2, namely dihydrolipoyllysine-residue succinyltransferase (DLST), cytochrome c oxidase subunit 5B (Complex IV), and persulfide dioxygenase ETHE1 were less-abundant proteins in D tumor samples." (PMID 39195201, 2024). "Nine CRGs were differentially expressed between tumor and normal tissues, among which NFE2L2, SLC31A1, FDX1, DLD, DLAT, and DLST were lowly expressed in tumor tissues, and ATP7B, CDKN2A, and GCSH were highly expressed in tumor tissues (p<0.05)." (PMID 37205181, 2023). "Cu transporter-related genes including ATP7A, SLC31A1, and TCA-related genes including DBT, DLST, and DLAT are differentially expressed between normal and tumor samples." (PMID 36438201, 2022). "The results showed that, in tumor samples, ATP7B, PDHA1, and SLC31A1 were significantly upregulated compared with normal tissues, whereas ATP7A, DLST, GCSH, LIAS, and LIPT1 were significantly downregulated." (PMID 36567939, 2022). "Gene expression profiling showed that SLC31A1, LIPT2, CDKN2A, and GCSH expression was increased in tumor tissues, while NFE2L2, NLRP3, ATP7A, DLD, MTF1, and DLST expression was decreased in tumor tissues compared with normal tissues." (PMID 37065485, 2023). "In tumor cell-enriched region, the expression of COPS5, DLAT, DLD, FDX1, NFE2L2, PDHA1 and PDHB in the high score group is higher than that in the low score group, while the opposite is true for DLST, GCSH and LIPT2 (P <0.05)." (PMID 36618352, 2022). "We found that FDX1, LIPT1, DLAT, PDHA1, PDHB, DLST, and ATP7A were significantly differentially expressed in tumor and nontumor tissues, with the standard of p < 0.05." (PMID 36975441, 2023).
cancer (13 papers, 2011 to 2024). A tumor composed of atypical neoplastic, often pleomorphic cells that invade other tissues. "In drug sensitivity analysis, the expression of CDKN2A, DLAT, PDHA1, and GLS was negatively associated with some or most drugs in the Cancer Therapy Response Portal database, and the expression of DLST positively correlated." (PMID 36588699, 2022). "Studies showed that OXPHOS can be upregulated to support the growth, survival, and migration of cancer cells, and upregulated DLST expression may pose a mechanism to increase OXPHOS." (PMID 36634214, 2023). "Our study showed that MRPL13 and its associated genes were significantly correlated with cuproptosis-related genes across cancers, with the most significant ones being FDX1, GCSH, DLST, and DLD." (PMID 37827692, 2023). "In total, 14 DECRs were identified, of which six regulators (MTF1, DLST, NLRP3, DBT, FDX1, and DLD) were downregulated in cancer tissues." (PMID 36672336, 2023). "The other genes upregulated belonged mainly to the “cancer” and cell death functions (NFAT5, BMO2K, DLST, IL6ST, FAM76B, and MGA)." (PMID 22619672, 2012). "Finally, the data on the gene expression profiles of cancer cell lines were integrated in the Genomics of Drug Sensitivity in Cancer (GDSC) database for drug sensitivity to fully explore the potential value of CDKN2A, DLAT, DLST, GLS, and PDHA1 genes as novel therapeutic targets." (PMID 36891150, 2023).
DLST also shares sentences with these, for which no sentence is quoted: prostate carcinoma (2 papers); anisakiasis (1); bladder cancer (1); brain infarction (1); Cerebral ischemia (1); chronic apical periodontitis (1); hepatocellular carcinoma (1); infection (1); liver cancer (1); liver fibrosis (1); mixed connective tissue disease (1); multiple myeloma (1); myocardial infarction (1); oral squamous cell carcinoma (1); ovarian carcinoma (1); pancreatic cancer (1); Parkinson disease (1); rheumatoid arthritis (1); spinocerebellar ataxia (1); thyroid carcinoma (1).